NLRP3 (NLR family pyrin domain containing 3)
Diseases named in the same sentence as NLRP3 in open-access papers (continued):
Sharing a sentence is not in itself a finding about the gene and the disease.
ischemic stroke (continued). "More specifically, ischemic stroke results in the translocation of p50 and p65 into the nucleus of microglia, leading to the activation of NF-κB and consequently triggering the transcription of target genes such as gasdermin D (GSDMD), NLRP3, IL-1β, and IL-18." (PMID 36677800, 2023). "In the literature, NLRP3 and NLRP1 represent two members of the family of inflammasomes best investigated, and it is now undisputed the pivotal role they played in the pathogenesis of ischemic stroke." (PMID 36297283, 2022). "Additionally, NLRP3 is overexpressed in cells exposed to OGD/R conditions, whereas NLRP3 inhibitor treatment decreases NLRP3 expression in ischemic stroke." (PMID 35222806, 2022). "Studies have shown that the NLRP3 inflammasome is a key factor in initiating the inflammatory response and that Dl-3-n-butylphthalide (NBP) can attenuate the inflammatory response and improve neuronal repair during ischemic stroke." (PMID 36013423, 2022). "QRT-PCR results on animal models of CPSP ischemic stroke showed that the expression levels of SIRT1 were downregulated, the activation of the NLRP3 inflammasome was upregulated, and the expression levels of IL-18 were upregulated in the brain tissues of the surrounding area of the injury." (PMID 36059399, 2022). "For example, in a mouse model of OGD studying ischemic stroke, elevated NLRC4 is thought to contribute to microglia pyroptosis without a significant association with NLRP3." (PMID 35937897, 2022). "Finally, NLRP3 inhibitors, such as MCC950, have been reported to successfully inhibit the activation of NLRP3 after ischemic stroke and alleviate cerebral infarct size, pyroptosis and neuronal apoptosis, and neurological dysfunction." (PMID 35328506, 2022). "Lemarchand, E. and colleagues reported that NLRP3 did not contribute to the extension of ischemic brain injury after ischemic stroke, as no protection to stroke was observed when applying NLRP3 inhibitor or knocking out NLRP3 in mice." (PMID 33967935, 2021). "After ischemic stroke, ATP accumulates in damaged and inflamed tissue, and the increase in ATP concentration activates P2X7R, leading to intracellular K+ efflux that activates the NLRP3 inflammasome." (PMID 34059091, 2021). "We demonstrate that QNDP could reduce inflammatory response and apoptosis via inhibiting NLRP3 inflammasome signaling pathway in cerebral ischemia in vivo and in vitro, further suggesting that QNDP is a novel treatment candidate for ischemic stroke." (PMID 32153398, 2020). "NOX inhibitor apocynin and nicotinamide adenine dinucleotide phosphate (NADPH) could inhibit the level of NLRP3, ASC, caspase-1, IL-1β and IL-18 in the cortex, improve the neurological functions, and decrease the infarct volume in ischemic stroke mouse model." (PMID 32581721, 2020). "Of course, our study did not prove the upstream mechanism by which HS inhibits NLRP3 inflammasome activation in ischemic stroke." (PMID 32529750, 2020). "While many studies propagate the inhibition of NLRP3, for example, by small molecule inhibitors such as MCC950, as a protective strategy after stroke, other data suggest a marginal role of NLRP3 after ischemic stroke." (PMID 32645874, 2020). "In summary, this study suggests that although there is a marked inflammatory response after ischemic stroke, NLRP3-dependent inflammation is not involved in exacerbation of the injury and thus does not represent a therapeutic target for ischemic brain injury." (PMID 31009361, 2019). "NLRP3 (Nucleotide-binding domain (NOD)-like receptor family, pyrin domain containing 3) is an inflammasome for which the structure and function have been extensively investigated, and it is activated in the onset of ischemic stroke." (PMID 27589720, 2016). "The negligible contribution of the NLRP3 inflammasome to stroke-induced brain injury, may in part, explain why Tet2-mediated CH did not worsen ischemic stroke outcomes in the current study." (PMID 39742155, 2024).
ischemic stroke (continued). "Therefore, the inhibition of STAT-1 and the NLRP3 inflammasome may play a neuroprotective role in CSVD and ischemic stroke." (PMID 36676165, 2023). "However, its effect on autophagy in NLRP3-driven neuroinflammation in ischemic stroke has not been evaluated." (PMID 37915409, 2023). "Additionally, the NLRP3 inflammasome could be a promising therapeutic target for the CNS diseases such as SCI, traumatic brain injury, and ischemic stroke." (PMID 35327480, 2022). "A previous study indicated that a lack of the NLRP3 inflammasome might enable rats to recover from cerebral injury after ischemic stroke by reducing infarcts and inflammatory responses." (PMID 36105479, 2022). "Moreover, NBP reduced NLRP3, CASP1, and IL-1β protein levels in ischemic stroke." (PMID 36013423, 2022). "In our work, circ_NLRP1 was identified to play a potential regulatory role during the pathophysiological process of ischemic stroke, as demonstrated by our data that showed the initiation of cell apoptosis could be evoked by increased circ_NLRP1 under OGD treatment or NLRP3 mediation." (PMID 34227902, 2021). "Also of note, the role of NLRP3 inflammasomes in the pathogenesis of ischemic stroke is not clear and requires further investigation." (PMID 32581721, 2020). "Therefore, the findings may not be applicable to studies related to NLRP3 in ischemic stroke published in other languages." (PMID 37088947, 2023). "However, bibliometric studies of NLRP3 in ischemic stroke are still lacking." (PMID 37088947, 2023). "However, there is no bibliometric analysis of NLRP3 in ischemic stroke to date." (PMID 37088947, 2023). "However, meisoindigo (3,30-linked bisindole, a second-generation derivative of indirubin) may inhibit the activation of NLRP3 inflammasomes and M1 polarization by inhibiting the TLR/NFκB signaling pathway, and it is expected to become a new drug for the treatment of ischemic stroke." (PMID 35008558, 2021). "Recent studies showed that various inflammasomes, containing NLRP1, NLRP2, NLRP3, NLRP10, NLR family card domain containing 4 (NLRC4), and absent in melanoma 2(AIM2) 35-39, are activated in ischemic stroke." (PMID 32788872, 2020). "Although NOX2 did not regulate NLRP3 or TXNIP in the umbilical vein endothelial cells, NOX2 deletion attenuated NLRP3 induction in the cerebral cortex of mice after ischemic stroke, as we observed after TBI." (PMID 28785377, 2017). "Although generally blocking NOX did not affect the activation of NLRP3 inflammasome in human and mouse cells, inhibiting of NOX2 could affect the activation in certain mouse models such as brain injury from ischemic stroke." (PMID 36204568, 2022). "Vice versa, expression of NLRP3, but not those of NLRC4 and AIM2, was markedly increased in response to recurrent stroke evoked in the contralateral cortex, probably due to the antecedent ischemic stroke as a priming step for NLRP3 inflammasome activation." (PMID 32635451, 2020).
myocardial infarction (218 papers, 2014 to 2026). Gross necrosis of the myocardium, as a result of interruption of the blood supply to the area, as in coronary thrombosis. "For instance, the Xin-Li formula has been shown to alleviate heart failure caused by hyperlipidemia and myocardial infarction in rats through Treg immunomodulation and inhibition of the NLRP3 inflammasome." (PMID 40860357, 2025). "Various diseases such as multiple sclerosis, inflammatory bowel diseases, autoimmune thyroiditis, anti-synthetase syndrome, as well as myocardial infarction, are associated with NLRP3 inflammasome." (PMID 39336475, 2024). "Studies have shown that the necrotic myocardium after myocardial infarction can act as DAMP to induce the assembly of NLRP3 inflammasome, causing cardiac inflammation and accelerating heart failure." (PMID 36378463, 2023). "Some studies have reported that loss of NLRP3 inflammasome alleviates inflammatory response and improves cardiac dysfunction induced by myocardial infarction (MI)." (PMID 35647057, 2022). "It is now well recognized that NLRP3 inflammasome/pyroptosis is implicated in the pathological process of acute myocardial infarction (AMI)." (PMID 36142531, 2022). "It has been shown that NLRP3 inflammasome is activated in ACS mainly in acute myocardial infarction, causing hyperinflammation and cardiac fibrosis." (PMID 36145367, 2022). "The association between the genotypes of SNPs in the NLRP3 downstream regulatory region and NLRP3 mRNA expression was investigated in the Swedish First-ever myocardial Infarction study consisting of DNA from 555 MI patients and 1016 healthy individuals." (PMID 34210954, 2021). "NLRP3 has been proved to be the most important sensor of aseptic inflammation caused by myocardial infarction." (PMID 34402164, 2021). "Endothelial-specific overexpression of MYC was sufficient to induce type H bone endothelial cells, whereas inhibition of NLRP3-dependent IL-1β production partially prevented the post-myocardial infarction loss of type H vasculature in mice." (PMID 34172720, 2021). "One study evaluated the impact of NLRP3 (exon 3) gene polymorphisms and serum NLRP3 levels on the risk of developing myocardial infarction (MI) in 69 patients and 53 controls." (PMID 34210954, 2021). "This study aimed to estimate the protective effects of H2 on myocardial infarction in rats and association with the amelioration of oxidative stress and NLRP3 inflammasome mediated pyroptosis." (PMID 34400901, 2021). "At day 3 after infarction, myocardial infarction was associated with an increase in ROS levels and NLRP3 inflammasome activity with age." (PMID 33022900, 2020). "The NLRP3 inflammasome and the associated inflammatory response have a role in the pathophysiology of a myocardial infarction (MI)." (PMID 32596261, 2020). "It was demonstrated that NLRP3 is closely associated with the myocardial infarct size and the death of cardiomyocytes." (PMID 31885905, 2019). "NLRP3 rs35829419 was associated with increased risk for macrovascular complications (P = 0.004), with myocardial infarction in particular (P = 0.052)." (PMID 26273672, 2015). "Our preliminary data suggest the role of NLRP3 polymorphism in diabetic macrovascular complications, especially in myocardial infarction." (PMID 26273672, 2015). "Inhibition of NLRP3 is an interesting target and may be associated with smaller myocardial infarct size." (PMID 40756604, 2025). "Furthermore, dysregulation of NLRP3 activity has been implicated in the pathogenesis of acute myocardial infarction (AMI)." (PMID 39594530, 2024). "Inflammasome (NLRP3) activation, subtypes of lymphocytes, interleukin 6, and some inflammatory biomarkers, are associated with larger infarct size and impaired ventricular function after myocardial infarction." (PMID 35837017, 2022).
myocardial infarction (continued). "TLRs are among the major receptors responsible for the priming of the transcription of proinflammatory genes via the NF-κB pathway during acute myocardial infarction; extracellular ATP released from necrotic cells caused the triggering of NLRP3 inflammasomes via P2X7." (PMID 34776995, 2021). "Furthermore, NLRP3 gene polymorphisms are strongly correlated with increased risk of macrovascular complications, particularly myocardial infarction, in diabetic patients." (PMID 33108705, 2020). "Furthermore, polymorphisms in the NLRP3 gene are strongly correlated with an increased risk of macrovascular complications, in particular myocardial infarction, in Type 2 diabetic patients." (PMID 29515457, 2018). "In myofibroblasts, NLRP3 inflammasome activation can cause the increase of activated IL-1β, which ultimately stimulates collagen synthesis, extracellular matrix protein expression, and myofibroblast differentiation, and participates in myocardial fibrosis and scar repair after myocardial infarction." (PMID 35401934, 2022). "Luteolin downregulates the expression of TLR4, MyD88, and NF-κB in a dose-dependent manner to inhibit NLRP3 inflammasome activation, consequently diminishing myocardial infarct size and enhancing left ventricular function." (PMID 39925805, 2025). "Ginsenosides can play a therapeutic role in diseases such as HF and myocardial infarction (MI) by regulating the NLRP3 inflammasome." (PMID 40572494, 2025). "A previous study emphasized the primary role of S100A8/9 and their downstream mediators (e.g. NLRP3) in shaping the inflammatory response following myocardial infarction." (PMID 40069854, 2025). "Another study revealed that MCC950, a well-known specific NLRP3 inhibitor, rescued myocardial damage and reduced cardiac fibrosis in a murine model of myocardial infarction." (PMID 41272654, 2025). "In acute myocardial infarction, the activation of NLRP3 inflammasome is critical, as shown by the reduced extension of infarct size in Nlrp3−/− mice, although its role in the ischemia–reperfusion (I/R) damage is still controversial." (PMID 38935171, 2025). "During myocardial infarction, mitochondrial damage and generation of reactive oxygen species activate the NLRP3 inflammasome upon reperfusion." (PMID 40835597, 2025). "Targeting NLRP3 is considered a promising therapeutic strategy for preventing myocardial infarction." (PMID 40141195, 2025). "Previous research showed that CoQ10 can alleviate inflammation partially via inhibiting the NLRP3/IL‐1β pathway to promote the recovery of cardiac function after myocardial infarction." (PMID 40951583, 2025). "NLRP3 is a prominent research topic in CVDs due to its involvement in myocardial infarction, cardiac hypertrophy, and atherosclerosis." (PMID 40404619, 2025). "Future research should focus on validating these results in animal models of myocardial infarction and exploring the potential of targeting NLRP3 inflammasome assembly as a therapeutic strategy in cardiovascular diseases." (PMID 40149903, 2025). "Following myocardial infarction, NLRP3 inflammatory vesicles are upregulated, potentially contributing to the progression of infarct size during ischemia-reperfusion." (PMID 40040697, 2025). "Histological studies have shown the presence of NLRP3 accumulations in cardiomyocytes and endothelial cells within the ischemic region and border zones during the early stages of acute myocardial infarction." (PMID 40227195, 2025). "In a mouse model of myocardial infarction, small interfering RNA silencing of Clec7a downregulates the expression of NLRP3, IL-1β, and IL-18, thereby attenuating myocardial injury." (PMID 40243488, 2025). "Research has identified the NLRP3 inflammasome as crucial in the development and adverse remodeling following myocardial infarction." (PMID 41194915, 2025).
myocardial infarction (continued). "Xin-Li formula attenuates heart failure induced by a combination of hyperlipidemia and myocardial infarction in rats via Treg immunomodulation and NLRP3 inflammasome inhibition." (PMID 41333015, 2025). "More recently, our group showed that neutrophil NLRP3 promoted the recruitment of neutrophils to the myocardium and the release of NETs in myocardium during a myocardial infarction murine model." (PMID 39654901, 2024). "Studies have shown that the coumarin analog isofraxidin alleviates myocardial infarction by inhibiting NLRP3 inflammasome activity." (PMID 39830344, 2024). "Inhibiting NLRP3 with MCC950 has been shown to suppress myocardial-infarction-induced inflammasome activation, consequently ameliorating cardiac inflammation and fibrosis, and enhancing cardiac function." (PMID 38791409, 2024). "Isofraxidin by suppressing NLRP3 inflammatory bodies plays a cardioprotective role in myocardial infarction." (PMID 39830344, 2024). "For example, IL-37 has been found to regulate macrophage programming through the YAP/NLRP3 pathway, indicating its therapeutic potential in myocardial infarction." (PMID 39121041, 2024). "In summary, we provide exciting evidence that neutrophil NLRP3 exacerbates myocardial infarction (MI) injury in the early phase through the local release of NETs and IL-1β." (PMID 38914598, 2024). "Data collected from 555 patients who experienced myocardial infarction and 1016 healthy individuals reveals a notable elevation in the expression of NLRP3, ASC, caspase-1, IL-1β, and IL-18 mRNA within atherosclerotic plaques compared to healthy arteries." (PMID 39594530, 2024). "Nucleotide-binding Oligomerization Domain-like Receptor Protein 3 (NLRP3) inflammasome is widely acknowledged as pivotal factor in specific cardiovascular disease progression, such as myocardial infarction, heart failure." (PMID 38650918, 2024). "The inflammasome of NLRP3 plays a key role in recognizing danger signals and inducing sterile inflammatory responses in myocardial infarction." (PMID 38268894, 2023). "Ranheim's study found that NLRP3 was upregulated in the myocardium after myocardial infarction, mainly in fibroblasts." (PMID 38268894, 2023). "The results showed that CGA pretreatment reduced myocardial infarction size and cTnT contents in serum, simultaneously reduced the levels of Lnc Neat1 expression and attenuated NLRP3 inflammasome-mediated pyroptosis in myocardial tissue." (PMID 37853132, 2023). "When the heart suffers from MIRI, the size and severity of myocardial infarction are positively correlated with caspase-1 and IL-1β levels, suggesting that NLRP3-induced pyroptosis exacerbates MIRI." (PMID 37098925, 2023). "NLRP3, IL-1β, IL-18, and hsCRP levels were significantly higher in myocardial infarction patients compared to the healthy group (p = 0.02, p < 0.001, p < 0.001, and p < 0.001, respectively)." (PMID 37763063, 2023). "Their studies showed a reduction in the formation of the NLRP3 inflammasome in macrophages in vitro and a decrease in inflammation after acute myocardial infarction in a mouse model following SP16 treatment." (PMID 36831299, 2023). "Salvianolate reduces atrial fibrillation by inhibiting the TGF-β1/Smad2/3 and TXNIP/NLRP3 inflammasome signaling pathways in rats after myocardial infarction, thereby inhibiting atrial fibrosis." (PMID 36909150, 2023). "It is known that glycolysis is involved in MF after myocardial infarction and NLRP3 inflammasome is activated by glycolytic inflammation, and HK1 is the first step of glycolysis." (PMID 38268894, 2023). "A recent study reported that plasma NLRP3 protein levels were 1.77 (0.7–5.79) ng/mL in patients with myocardial infarction and 0.77 (0.4–0.9) ng/mL in the control group." (PMID 37763063, 2023). "Inflammasomes, especially NLRP3, are believed to be key players in various cardiovascular events, such as acute myocardial infarction, myocarditis or pulmonary hypertension." (PMID 37239853, 2023).